ACE (angiotensin I converting enzyme)
Diseases named in the same sentence as ACE in open-access papers (continued):
Sharing a sentence is not in itself a finding about the gene and the disease.
COVID-19 (continued). "Part of the increased level of EVs, which is characteristic of severe COVID-19 and associated ARDS, is due to endothelial injury, whether released from the pulmonary capillary vasculature (angiotensin-converting enzyme+ [ACE+]; von Willebrand Factor− [vWF−]) or systemic vasculature (ACE−; vWF+)." (PMID 36268783, 2022). "In addition, COVID-19-mediated ACE-II downregulation shifts angiotensin I (AT-I) into the angiotensin converting enzyme/angiotensin II/angiotensin II type I receptor pathway (ACE/AT-II/AT-1R), thus increasing the activity of angiotensin II (AT-II)." (PMID 36077865, 2022). "The RAS is affected in COVID-19, and ACE could be a therapeutic target." (PMID 35330406, 2022). "However, due to ACE2 is critically important in the cellular entry of SARS and SARS-CoV-2, it is possible that hypertensive COVID-19 patients treated with drugs that increase ACE2, e.g., ACE inhibitors and AT1R blockers, are at a higher risk for the development and severity SARS-CoV-2 infection." (PMID 34973134, 2022). "All three CHM formulas not only affect ACE but also blood sugar control related target proteins such as DPP4 and GHSR, meaning that they can help reduce the risk of precipitating hyperglycemia caused by COVID-19 as well as lower the blood sugar level of pre-existing DM." (PMID 35890093, 2022). "Patients with COVID-19 are more likely to have a serious infection, or to die, if they also have comorbidities, including cardiovascular and cerebrovascular disease, conditions commonly treated with ACE inhibitors (ACEi) or angiotensin receptor blockers (ARBs)." (PMID 35162972, 2022). "Therefore, the intake of oat products provides a rich source of phytochemicals that provides health benefits such as decreasing high blood pressure and influencing the immunotherapies against infections such as COVID-19 due to the presence of inhibitory peptides of ACE and of β-glucans." (PMID 37430980, 2022). "However, it is debatable whether it is safe to use ACE inhibitors and ARBs in hypertensive patients with COVID-19." (PMID 35075396, 2022). "Thus, in contrast to ACE2, the ACE gene sequence may influence the results of the COVID-19 clinical trial." (PMID 36553622, 2022). "Numerous components in Sargassum, including ACE inhibitory peptides and soluble dietary fibers (e.g., fucoidan, porphyran, etc.), could minimize the ACE dominance caused by SARS-CoV-2 infection, enhancing the effectiveness of the COVID-19 vaccine." (PMID 36605100, 2022). "It is reported that increased ACE concentrations lead to increased levels of angiotensin II, which might be responsible for the severe lung injury in COVID-19 patients, while inhibiting the angiotensin II-signaling pathway and/or RAAS, through ACE2, has been shown to protect against lung damage." (PMID 36558489, 2022). "There has been much speculation about how ACE inhibitors or ARBs might alter expression of the ACE2 protein, and thereby potentially alter host susceptibility to infection with SARS-CoV-2 or the progression, severity, and tissue-specific pathology of COVID-19." (PMID 35359831, 2022). "Although knowing the genotype of these ACE variants does not directly modify the clinical course of these patients, identifying those most at risk of severe COVID-19 will allow better monitoring of these patients to apply all available means to improve their prognosis." (PMID 34489863, 2021). "Thus, it could be said that both COVID-19 and RA share a common mechanistic pathway of immunopathogenesis mediated through aberrant ACE/ACE2 activities." (PMID 34943795, 2021). "Interestingly, we also found that the COVID-19–related signal pathway was enriched in the healthy controls with higher ACE expression, indicating the DD genotype with increasing ACE activity may be the potential susceptive factor for the COVID-19." (PMID 35095487, 2021).
COVID-19 (continued). "Therefore, the imbalance of ACE2/ACE and the Ang-II/AT1R axis could explain the increase in cytokine levels in COVID-19 patients, as well as the associated lung damage." (PMID 34721388, 2021). "Thus, the peptides in edible seaweeds might function as dietary ACE inhibitors, leading to a protective effect against COVID-19 by reducing the degree of ACE/Ang II/ATR1 axis dominance." (PMID 34360741, 2021). "The conventional RAS (ACE/Ang II/AT1R) axis activation in parallel with non-conventional (ACE2/Ang 1-7/Mas) axis down-regulation was proposed to be the underlying factors leading to severe COVID-19 outcome in hypertension." (PMID 34012410, 2021). "Amid the COVID-19 pandemic, concerns have been raised that the use of renin-angiotensin-aldosterone-system (RAAS)-blocking agents, such as ACE inhibitors (ACEI) and angiotensin receptor blockers (ARB) may increase the susceptibility to or aggravate the severity of COVID-19." (PMID 34059140, 2021). "Similar to the ACE and PLAT Alu I/D polymorphism, the F13B variation observed across the human population could be an important biological factor when considering the variable individual response to COVID-19." (PMID 33390179, 2021). "Polymorphism studies in countries that have a high COVID-19 prevalence showed that the insertion allele of the ACE deletion/insertion (D/I) polymorphism correlates with COVID-19 prevalence although the ACE enzyme has no direct impact on the SARS-CoV-2 pathogenesis." (PMID 34803443, 2021). "Indeed, several recent studies hypothesized that COVID-19 patients receiving ACE-inhibitors may be subject to poorer outcomes, whereas other investigators argued that the usage of ACE-inhibitors could be beneficial in COVID-19 infection." (PMID 33544720, 2021). "Additionally, other studies confirmed that pre-existing ACE inhibitors or ibuprofen intake are possibly not the factors causing severity of COVID-19." (PMID 33001409, 2021). "The balance between angiotensin-converting enzyme (ACE) 1 and ACE 2 activity as the host factors has been implicated in the pathogenesis of respiratory diseases and could play a role in the severity of COVID-19." (PMID 33494706, 2021). "Second, angiotensin-converting enzyme (ACE-2), which is highly expressed in adipose tissue, acts as a receptor for the entry of SARS-CoV-2; this may lead to an increased risk of infection as well as of severe outcomes in patients with COVID-19." (PMID 34066585, 2021). "This higher elevation of ACE levels in individuals with the GG genotype was also confirmed in hypertensive patients (p<0.05), although this elevation was not directly associated with the severity of COVID-19." (PMID 34489863, 2021). "It not only plays a significant role in anti-inflammation and anti-ACE-2, but also significantly improves the clinical symptoms of fever, dry cough and shortness of breath, suggesting that licorice is expected to be a candidate drug for adjuvant treatment of patients with early / mild COVID-19." (PMID 34899289, 2021). "It has been proposed that, in cases of COVID-19, blood platelet activation may be dysregulated via alterations in the function of angiotensin converting enzyme (ACE), and by changes in the angiotensin II/angiotensin type 1 receptor: a G-protein coupled receptor." (PMID 33808640, 2021). "Therefore, considering the imbalance of the RAS family (overactivation of the ACE-Ang II-AGTR1 axis) in COVID-19, a combination of ACEIs/ARBs and ICIs could be considered for use in cancer patients infected with SARS-CoV-2." (PMID 34671200, 2021). "Therefore, it is hypothesized that increasing ACE2 via ARB and ACE inhibitors is contraindicated for COVID-19 patients." (PMID 33801921, 2021). "The use of ACE inhibitors or Ang II type 1 receptor blockers had no clear association with COVID-19 incidence and all-cause mortality; they may be protective for patients with hypertension." (PMID 35096872, 2021).
COVID-19 (continued). "It has been hypothesized that in the initial phase of SARS-CoV-2 infection, a RAS imbalance with increased activation of the classical RAS arm (i.e., renin/ACE/angiotensin II axis) leads to alterations in hemostasis and a hyperinflammatory state, triggering COVID-19." (PMID 34945736, 2021). "Moreover, a recent study has shown that Coronavirus disease (COVID-19) patients with hypertension treated with ACE inhibitors and AT1R blockers had different values of viral load and an attenuation of the inflammatory response, likely through the inhibition of IL-6 levels." (PMID 32344526, 2020). "However, in the same study, neither ACE inhibitors nor ARBs showed an independent association with COVID-19 in patients with mild-to-moderate disease or in those with severe disease." (PMID 33195473, 2020). "ACE inhibitors and ARBs may play a protective role in the treatment of COVID-19 cases." (PMID 32760350, 2020). "While it is still controversial whether RAAS inhibitors are to be administered to COVID-19 patients, it is certain that the therapy with ACE inhibitors and angiotensin receptor blockers (ARBs) should definitely not be discontinued in patients with preexisting cardiovascular diseases." (PMID 33240098, 2020). "Various authors have recommended caution when prescribing ACE inhibitors or angiotensin-receptor blockers (ARBs) in COVID-19 patients with cardiovascular comorbidity, as this medication can increase ACE2 levels, which could potentially lead to a more severe health outcomes." (PMID 32709002, 2020). "Second, serum ACE activity could not serve as an independent risk factor for the severity of COVID-19 in this study." (PMID 33238910, 2020). "On the other hand, a recent COVID-19 related study showed decreased expression of ACE in combination with increases in ACE2 likely causing bradykinin-related increases in vascular dilation, vascular permeability and hypotension, explaining many of the symptoms being observed in COVID-19." (PMID 33233425, 2020). "Interestingly, there is hypothesis of the link between angiotensin converting enzyme (ACE) inhibitors and COVID-19." (PMID 32295188, 2020). "Although the presence of ACE2 was not specifically characterized in those studies, these data suggest that circulating MPs are key modulators of various ACE activities within the vascular compartment and could therefore act as an important mediator of COVID-19 pathogenicity." (PMID 32486469, 2020). "Extrapolating data from SARS-CoV to SARS-CoV-2, one may postulate that the imbalance in the signaling and actions of products of ACE/ACE2, generated by the loss of ACE2 cell surface expression due to SARS-CoV-2 infection, may lead to severe acute respiratory failure in COVID-19." (PMID 33329052, 2020). "However, some studies suggest that ACE inhibitors and ARBs could benefit patients with COVID-19 since ACE2 converts angiotensin II to angiotensin, which may have beneficial vasodilatory and anti-inflammatory properties." (PMID 32585805, 2020). "In one of the largest series reporting COVID-19 patients published so far, the use of ACE inhibitors before infection was shown to reduce mortality by 33%, representing the most effective independent factor, among those analyzed, that could protect patients from a lethal outcome." (PMID 33177594, 2020). "Indeed, hypertensive patients are treated with these drugs which may interfere with the COVID-19 clinical course by modulating the mechanisms evidenced above (ACE/ACE2-ATR1-Cholesterol-HDAC axis)." (PMID 33363465, 2020). "Therefore, serum ACE activity could be used as a marker to reflect the clinical condition of COVID-19." (PMID 33238910, 2020). "BK-evoked sensitization of airway sensory nerves is believed to be the main mechanism for ACE-inhibitor-induced dry cough: considering that dry cough is very frequently observed in COVID-19 patients, this pathway could in part explain the pathogenesis of this symptom." (PMID 32849666, 2020).
COVID-19 (continued). "The resulting increase in the ACE/ACE2 ratio indicates a progressive shift toward the pro-inflammatory arm of the RAS, providing mechanistic insight into the COVID-19 pathophysiology." (PMID 42043254, 2026). "The results demonstrated that high doses of isochlorogenic acid C inhibited FXR/RXR, DPP4, JAK2, ACE, CNGA1, BLT1, COX-2, and 5-LOX, suggesting its potential to modulate COVID-19-related inflammatory pathways." (PMID 40076279, 2025). "Earlier, in unrelated research, we have used DBK to monitor the serum activity of ACE and basic carboxypeptidases N and B2 (CPN, CPB2) in two clinical studies on Complex-Regional Pain Syndrome and COVID-19." (PMID 40572588, 2025). "The resulting network revealed several highly connected hub proteins, including IL1B, IL6, TNF, ACE, and REN, which are central regulators of inflammatory and cardiovascular pathways known to play key roles in COVID-19 pathogenesis." (PMID 41471341, 2025). "The imbalance between ACE and ACE2, induced by SARS-CoV-2, precipitates renin–angiotensin–aldosterone system (RAAS) activation, which ultimately drives the progression of COVID-19." (PMID 39337343, 2024). "They reported that endothelial dysfunction occurs as a result of the SARS-CoV-2 spike protein interacting with an angiotensin-converting enzyme (ACE-2) and that ACE-2 expression increases in COVID-19." (PMID 38626032, 2024). "ACE2 plays a crucial role in controlling the renin–angiotensin–aldosterone system (RAAS), and SARS-CoV-2 disrupts the equilibrium between ACE/ACE2 and activates the RAAS, ultimately resulting in the advancement of COVID-19." (PMID 38921948, 2024). "BALB/c male mice were subjected to PM2.5 sub-acute exposure to study its effects on ACE2 and ACE, COX-2, HO-1 and iNOS proteins levels, in the main organs concerned with the pathogenesis of COVID-19." (PMID 36901403, 2023). "The excessive DBK1–5 values in some convalescent patients, however, point to overactive ACE and the dysregulation of the RAS, as observed in acute COVID-19." (PMID 37511837, 2023). "SARS-CoV-2 disrupts the ACE/ACE-2 balance and activates the RAAS, ultimately, leading to COVID-19 development, particularly in individuals with comorbidities." (PMID 37048725, 2023). "Therefore, an imbalance between ACE and ACE2 followed by an increased level of Ang II as well as primary and secondary inflammation induced by SARS-CoV-2 infection may be plausible causes of neuronal complications in COVID-19 patients." (PMID 37575318, 2023). "In COVID-19-mediated ALI, ACE2 depletion by SARS-CoV-2 spike protein binding disrupts the balance between ACE and ACE2." (PMID 37763673, 2023). "Conversely, use of ACE inhibitors (ACEis), which increase ACE2 cell expression, seemed to improve the prognosis of hypertensive patients with COVID-19." (PMID 37476705, 2023). "ACE belongs to the renin–angiotensin–aldosterone system (RAAS), which has a significant role in COVID-19; this enzymatic chain not only controls the pulmonary system, but also regulates the renal and circulatory systems." (PMID 36673116, 2023). "The ACE/Angiotensin 2/PKC/NOX2 pathway, which is initiated by RBD-induced hACE2 shedding, represents a major therapeutic target in COVID-19 vasculopathy." (PMID 37638055, 2023). "Therefore, alteration of the ACE/ACE2 ratio may aggravate COVID-19 symptoms." (PMID 38020136, 2023). "Both ACE-2 and IFITM-3 SNPs were amongst the highest determinants of COVID-19 severity, together with IL-6, CRP, D-dimer, ferritin, preexisting comorbidities, and age." (PMID 38155729, 2023). "Distribution of ACE-1 (rs4343), TMPRSS2 (rs12329760) and ACE-2 (rs908004) SNPs Genotypes among COVID-19 positive patients and healthy controls." (PMID 37426824, 2023). "Considering the pathophysiology of COVID-19, SARS-CoV-2 enters the host cells via the receptors of angiotensin-converting enzyme (ACE) type 2 with the additional help of transmembrane serine protease 2 (TMPRSS2) as the essential protease." (PMID 35369001, 2022).
COVID-19 (continued). "In detail, should we continue blocking the RAAS in COVID-19 patients and is one RAAS blockade better than the other (ACE-inhibition versus AT1R-blockade)?" (PMID 35685188, 2022). "The use of angiotensin-converting enzyme (ACE) inhibitors and angiotensin receptor blockers (ARB) in COVID-19 patients was initially very controversial." (PMID 35056603, 2022). "Additionally, ACE2 is a target of ACE inhibitor class drugs, to which Africans generally respond poorly compared to other ethnicities, suggesting the presence of genetic variation that may also impact COVID-19." (PMID 36263375, 2022). "On the other hand, the dysfunctional balance of ACE/ACE2 is one of the main factors that lead to COVID-19-induced lung injury; therefore, compensation of ACE2 to balance ACE/ACE2 function should be a promising way to alleviate COVID-19-induced lung injury." (PMID 35287354, 2022). "This study detected a correlation of the measured serum ACE and CPN activities with the damage of the heart muscle, blood clotting and fibrinolysis, inflammation and limited liver function in COVID-19." (PMID 35330406, 2022). "Bioactive compounds in this plant target the significant COVID-19 responsible receptors such as MAPK14, ACE, TLR4, and MAPK8, which makes this plant an ideal candidate for treating this deadly infection." (PMID 36144690, 2022). "The imbalance of RAS in COVID-19, via the virus-mediated down-regulation of ACE2, favorizes the pro-inflammatory ACE/Ang II/AT1R axis leading to the cytokine storm syndrome and consequent cellular damage." (PMID 35566253, 2022). "The involvement of the renin–angiotensin system (RAS) in the pathophysiology of coronavirus disease 2019 (COVID-19) is commonly discussed, because angiotensin-converting enzyme 2 (ACE2) is a functional receptor of SARS-CoV-2, and at the same time, a counter-balance for ACE in the RAS." (PMID 35458690, 2022). "The ACE inhibition of these mushrooms can indirectly restore the ACE/ACE2 ratio, thus providing COVID-19’s treatment effect." (PMID 35889330, 2022). "The ACE inhibitors upregulate ACE2 receptors, thus they can potentially worsen the state of COVID-19 patients treated with ACE inhibitor therapy." (PMID 35745658, 2022). "Studies have shown that the highest expression of ACE with TMPRSS2 is detected in nasal secretory cells, which correlates with COVID-19 pathology." (PMID 35743381, 2022). "Thrombolytics, anticoagulants, anti-inflammatory therapy, antivirals, angiotensin-converting enzyme (ACE) inhibitors, and angiotensin receptor blockers are among the potential treatments for COVID-19-related stroke patients (ARBs)." (PMID 35645351, 2022). "We have recently shown that ACE and carboxypeptidase N (CPN) serum activity correlated with disease severity in a cohort of 45 hospitalized and 26 convalescent COVID-19 patients." (PMID 35458690, 2022). "As we have seen, there is sufficient evidence to affirm that ACE inhibitors and sartans, classic RAAS targeting drugs, can be used safely in patients with COVID-19; however, more data is needed to understand if they can be beneficial." (PMID 34359922, 2021). "ACE2 mediated activation of ACE/AngII/AT1R axis leading to hyperactivation of NFKBIA, ultimately precipitating cytokine storm in COVID-19 patients." (PMID 33602138, 2021). "It does not mean that this problem is unequivocally resolved and does not require further basic research and clinical observations on the effects of ACE inhibitors and AT1R blockers in patients infected with SARS-CoV2 and COVID-19." (PMID 33925881, 2021). "Although the status of circulating and lung ACE levels in COVID-19 patients is unclear, the ability of SARS-CoV-2 binding specifically to ACE2 decreases its expression and activity suggesting upregulation of ACE/Ang-II-mediated activities." (PMID 32901433, 2021).